IL17A (interleukin 17A)
Diseases named in the same sentence as IL17A in open-access papers (continued):
Sharing a sentence is not in itself a finding about the gene and the disease.
Autoimmunity (continued). "Deletion of IL-17A and IFN-γ in the CD25KO (creating a CD25/IL-17/IFN-γ TKO) ameliorates dacryoadenitis and improves glandular function, demonstrating that IFN-γ is key to the autoimmunity in this model." (PMID 25889094, 2015). "Moreover, IL-17A+Foxp3+CD4+ cells have been observed in skin lesions of patients with severe psoriasis and in experimental models of autoimmunity." (PMID 34539668, 2021). "Of the two highly homologous IL-17 family members, IL-17A and IL17F, we focused on IL-17A, because, unlike IL-17F, IL-17A appears to mediate autoimmunity." (PMID 27095999, 2015). "Our observations illustrate that IL-17A promotes IL-1β production from orbital fibroblasts via the NLRP3 inflammasome in GO, and cytokines subsequently released may induce more inflammation and autoimmunity." (PMID 37109536, 2023). "It has been proposed that ongoing autoimmunity in the EAE mouse model is likely to represent the defective function of Tregs and lose FOXP3 expression under inflammatory conditions and can be induced to express proinflammatory cytokines, such as IL-17 and IFNγ (IFNγ+ FOXP3+ IL-17A+) (52, –, 54)." (PMID 37615438, 2023). "However, the relationship between such early innate/inflammatory events mediated by the TH17/IL-17A system and the role TH17 cells play in subsequent autoimmunity remains unknown, especially in light of the multiple functions now associated with the TH17 cell populations." (PMID 21182786, 2010). "However, some researchers found that IL-17A/TH17 cells downregulated type 1 collagen production upon the differentiation of fibroblasts into myofibroblasts, concluding that said mechanism may not be driven by fibrotic activity but by autoimmunity." (PMID 38674328, 2024).
inflammatory bowel disease (491 papers, 2008 to 2026). A spectrum of small and large bowel inflammatory diseases of unknown etiology. "IL-17A inhibitors can cause upper respiratory tract infection, nasopharyngitis, headache, Candida infection, and inflammatory bowel disease have also been reported in some patients." (PMID 37485474, 2023). "IL-17A acts as a pathogenic cytokine in a variety of inflammatory diseases, including multiple sclerosis, inflammatory bowel disease, and uveitis." (PMID 38007487, 2023). "In inflammatory bowel disease, highly pathogenic Th17 cells expand and secrete proinflammatory cytokines, such as IL-17A and IL-22, which can cause a wide range of inflammatory responses." (PMID 33553436, 2021). "Reduction of IL-17a production in intestine has been associated with relief of symptoms related to inflammatory bowel diseases, such as ulcerative colitis." (PMID 25162711, 2014). "Nonetheless, we were intrigued about the augmented levels of Il17a and Il1r1 transcripts found in cluster 3 RORγtS182A colonic Th17 cells, as the elevated IL-1β level was associated with increased disease severity in patients with inflammatory bowel diseases." (PMID 35294872, 2022). "Though inhibiting critical immune mediators may carry an increased risk of infections, the safety profile of anti-IL-17A therapies is generally favorable except for higher Candida infection and inflammatory bowel disease." (PMID 31881026, 2019). "Pathogenicity may reflect the modest switch to expression of the pathogenic cytokines IFNγ, IL-17A, and F, although in other models of inflammatory bowel disease (IBD), the percentage of IFNγ producers can be much higher." (PMID 26834739, 2015). "In Inflammatory Bowel Disease (IBD), patients with Crohn's disease have a loss of colonic or ileum IL-22-producing ILCs (including ILC3s) and an increase in IFNγ/IL-17A-producing ILCs." (PMID 30984202, 2019). "For example, blockade of IL-17A was ineffective and even exacerbated inflammatory bowel disease in some patients, due to the critical role that IL-17A plays in the maintenance of epithelial barrier homeostasis." (PMID 40749055, 2025). "In individuals with a predisposition to inflammatory bowel disease (IBD), strong blockade of IL-17A by secukinumab may induce immune polarization toward the Th1 axis." (PMID 40746559, 2025). "New-onset inflammatory bowel disease cases challenge the traditional view of IL-17A as purely pro-inflammatory in gut mucosa." (PMID 40408459, 2025). "Patients with inflammatory bowel disease have higher levels of IL-17A, which leads to intestinal inflammation and contributes to tissue damage." (PMID 38892253, 2024). "Additionally, the genes of pro-inflammatory cytokines associated with inflammatory bowel diseases (IBD), such as Il17a, Il23a, and Ifng31 were all upregulated in TCRγδ+CD8αα+ IELs in TGF-β receptor I-deficient mice." (PMID 37253786, 2023). "There are reports of inflammatory bowel disease induced or aggravated by IL-17A inhibitors, thus IL-17A inhibitors should be used with caution in SpA patients with active inflammatory bowel disease." (PMID 37485474, 2023). "A study suggested a positive link between NOS-derived NO and IL-6, IL-17A, and IL-23 plasma levels in inflammatory bowel disease patients." (PMID 36986188, 2023). "On the other hand, IRF4 is also thought to control ROR-γt-dependent Th17 inflammatory bowel disease by regulating il17a promoter activity." (PMID 33803441, 2021). "On the other hand, NKp44-ILC3 have been described to accumulate and to aggravate inflammation due to their secretion of IFNγ and IL-17A, respectively, especially during inflammatory bowel disease (IBD)." (PMID 35003122, 2021). "While homeostatic IL-17 production has been attributed protective functions in intestinal health and host-commensal microbe interactions, elevated IL-17A/F production has also been associated with the pathogenesis of inflammatory bowel disease (IBD)." (PMID 32117267, 2020).
inflammatory bowel disease (continued). "Accumulating evidence demonstrates that IL-17A is related to a variety of inflammatory and autoimmune diseases such as inflammatory bowel diseases (IBD) and multiple sclerosis." (PMID 32611373, 2020). "Nonetheless, IL-17A inhibitors should be used with caution in patients with a history of inflammatory bowel disease." (PMID 30109481, 2018). "Pooled safety data from clinical trials of ixekizumab and secukinumab, however, show that exacerbation of inflammatory bowel disease rarely occurs with IL-17A inhibition." (PMID 30109481, 2018). "Friedrich and colleagues showed that IL-17A strongly induced TNF-α expression in inflammatory bowel disease." (PMID 27190491, 2016). "Th17 cells produce IL17A and have been suggested to be the critical driver of autoimmune tissue inflammation, including collagen-induced arthritis, inflammatory bowel disease (IBD), and experimental autoimmune encephalomyelitis (EAE)." (PMID 26509545, 2015). "Our data suggest that while IL-17A plays a protective role in autoimmune cholangitis, it has a pro-inflammatory role in inflammatory bowel disease." (PMID 25133396, 2014). "We recently showed that IL-17A is increased in the inflamed areas of patients with inflammatory bowel disease (IBD)." (PMID 23834907, 2013). "PGE2 increased the numbers of CD4+IL-17A+ T cells and neutrophils in the colonic tissue in a mouse model of experimental inflammatory bowel disease." (PMID 22590492, 2012). "Besides, IL-23-induced IL-17A production by ILC3s can drive inflammatory bowel disease (IBD) in Tbx21−/−Rag2−/− ulcerative colitis (TRUC) mice." (PMID 41467015, 2025). "Secukinumab, a monoclonal antibody targeting interleukin-17A, is effective for treating moderate-to-severe plaque psoriasis but may induce paradoxical inflammatory bowel disease, particularly Crohn’s disease." (PMID 40746559, 2025). "Nevertheless, efforts to impede IL‐17A signaling in inflammatory bowel disease, such as Crohn's disease, through the use of antibodies (such as secukinumab, brodalumab, or ixekizumab) have encountered constrained success, frequently resulting in the exacerbation of inflammation." (PMID 38585232, 2024). "The bidirectional effect of Parasutterella on gut inflammation may serve as a possible mechanism by which IL-17A inhibitors contribute to inflammatory bowel disease." (PMID 38482003, 2024). "Seven genes IL10, IL4, IL6, IFNG, IL1B, TNF and IL17A, were engaged in Inflammatory bowel disease." (PMID 36989283, 2023). "Moreover, increased levels of IL-17A and IL-17F expression are detected in the inflamed guts of patients with inflammatory bowel disease (IBD)." (PMID 34122457, 2021). "There is strong evidence to support the role of γδ T cell-derived IL-17A in the protection of epithelial barriers in the intestinal mucosa; as such, IL-17A blockade may exacerbate inflammatory bowel disease." (PMID 30109481, 2018). "Furthermore, TLR4 possibly activate down-stream JAK/STAT pathway to secrete IL-17A in inflammatory bowel disease, which suppressed WNT pathway through stimulating DKK1 in intestinal stem cells." (PMID 29228588, 2017). "Furthermore, genetic studies have revealed the presence of polymorphisms in the genes IL17A / F and IL23R which are associated with inflammatory bowel disease and some cancers such as bladder, breast, uterus and gastric cancer." (PMID 26083022, 2015). "The expression levels of IL-17A and IL-17F are significantly elevated in the inflamed mucosa of patients with inflammatory bowel disease (IBD)." (PMID 40143073, 2025). "Application of tofacitinib, a drug approved for treatment of RA and inflammatory bowel disease (IBD), on TNF-α/IL-17A–triggered BMS astrocyte/NGN2-neuron cocultures resulted in the loss of BMS astrocytes’ ability to protect neurons against the TNF-α/IL-17A–induced neurite damage." (PMID 37219933, 2023).
inflammatory bowel disease (continued). "Intervention with AG490 (a highly selective JAK2 inhibitor) in a rat model of inflammatory bowel disease (IBD) significantly decreased the levels of IL-6 and IL-17A and increased the levels of IL-10, suggesting a protective effect on IBD." (PMID 35590365, 2022). "Additionally, IL-17A production has been observed in subpopulations of T regulatory cells, and it is hypothesized that these cells may be protective against inflammatory bowel disease." (PMID 30109481, 2018). "In addition, the increase in Parasutterella after IL-17A inhibitor therapy may be related to the development of inflammatory bowel disease in some PSO patients, as higher levels of Parasutterella are associated with chronic inflammation in Irritable Bowel Syndrome (IBS)." (PMID 38482003, 2024). "Interleukin (IL)-17A is essential for intestinal mucosal integrity, contributing to the prevention of detrimental immunity such as infectious colitis and inflammatory bowel disease (IBD)." (PMID 38060157, 2024). "Specifically, conditions such as inflammatory bowel disease (IBD) and celiac disease are characterized by an increased expression of the cytokine genes IL-8 and IL-17A in intestinal biopsy specimens." (PMID 39596886, 2024). "Th17 cells have been reported to infiltrate massively into the inflamed intestine and secrete pro-inflammatory cytokines of IL-17A for recruiting neotrophils, which triggers and amplifies the inflammatory pathogenesis in inflammatory bowel disease (IBD) patients." (PMID 36792629, 2023). "IL-17A has recently emerged as a protective cytokine for inflammatory bowel diseases, as a result of which clinical trials with secukinumab or brodalumab in patients with IBD resulted in enhanced Candida infections and increased intestinal inflammation." (PMID 36289634, 2022). "The rise of GM-CSF may explain, to some extent, why the use of anti-IL-17A monoclonal antibodies alone aggravates symptoms seen in inflammatory bowel disease (IBD)." (PMID 34557201, 2021). "In addition, the combination of IFN-γ, IL-17A/F and IL-23, referred to in the present study as cytokine combination, was designed for a disease model such as inflammatory bowel disease (IBD) or experimental autoimmune encephalomyelitis (EAE)." (PMID 32443511, 2020). "Here we show that CD4+Foxp3+Tregs produce the effector cytokine IL-17A during oropharyngeal candidiasis (OPC) and inflammatory bowel disease in a TLR-2/Myd88 signaling dependent manner." (PMID 25790134, 2015). "Our data would further imply the potential of modulating IL-17A in patients with PBC, but also caution against such usage in inflammatory bowel disease." (PMID 25133396, 2014). "The role of IL-17A in inflammatory bowel disease (IBD) has been extensively studied, but has not been fully understood." (PMID 38060157, 2024). "In laminar propria lymphocytes of inflammatory bowel disease patients, LIF-activated STAT4 inhibits activation of the STAT3-dependent Il17a/Il17f promoter, while in intestinal epithelial cells, LIF bypasses abnormally low STAT4 levels and induces YAP gene expression by activating STAT3." (PMID 33505963, 2020). "This non-linear relationship between IL-17 and IL-23 extends to inflammatory bowel disease, where IL-23 blockade improves gut inflammation but neutralizing IL-17A does not." (PMID 33329560, 2020). "Interleukin 17F is closely related to IL-17A and its role in the development of inflammatory bowel disease remains not well-established." (PMID 32724117, 2020). "Interestingly, in patients with inflammatory bowel disease and anti-TNF-α therapy the increase in Th17 and IL-17A levels indicates a better outcome, while the opposite is observed in MS patients, who worsen as IL-17 increases under TNF-α blockade." (PMID 41142785, 2025).
inflammatory bowel disease (continued). "By integrating transcriptomic data from human inflammatory bowel disease (IBD) colonic biopsies with mouse dorsal root ganglion (DRG) single‐cell data, we identify IL‐17A and its receptor IL‐17RA as potential mediators of nociceptor activation." (PMID 40827457, 2025). "During the pathogenesis of inflammatory bowel disease (IBD), the formation of NETs can activate the production of various pro-inflammatory factors, such as IL-1β, TNF-α, and IL-17A." (PMID 40620701, 2025). "AU and inflammatory bowel disease (IBD) history were less frequent in the ETN and anti-IL17A groups than in the anti-TNF mAb." (PMID 34271991, 2021). "Using qPCR and IHC, we compared β-catenin, PPARγ, COX-2, and IL-17A in the colonic mucosa of patients with sporadic CRC, inflammatory bowel disease (IBD), and irritable bowel syndrome (IBS), against a normal control population." (PMID 30186819, 2018). "They suggested that there is the presence of a potential therapeutic role for combined blockage of IL17A and IL17F in the treatment of inflammatory bowel disease, rather than blocking either cytokine alone." (PMID 26083022, 2015).
systemic lupus erythematosus (390 papers, 2009 to 2026). An autoimmune multi-organ disease typically associated with vasculopathy and autoantibody production. "IL-17A has been reported to be a key pro-inflammatory cytokine associated with hypertension in individuals suffering from autoimmune disorders such as systemic lupus erythematosus (SLE) and Crohn’s disease." (PMID 37266014, 2023). "IL-17F has also been shown to drive renal tissue injury in lupus mice, suggesting the pathogenic functions of IL-17A and IL-17F in lupus pathogenesis." (PMID 34122457, 2021). "Despite the overwhelming evidence that IL-17 contributes to lupus pathology, IL-17A deficiency in lupus-prone MRL/lpr mice or IL-17A neutralization in NZB/NZW mice did not affect the course of nephritis." (PMID 29868033, 2018). "Similar to Th17 cells, Tc17 cells secrete IL-17A and IL-17F and are implicated in the pathogenesis of some human autoimmune diseases, such as psoriasis and systemic lupus erythematosus (SLE)." (PMID 24489575, 2013). "In Fc gamma receptor IIb- (Fcgr2b-) deficient mice that develop fatal lupus pathology, IL-17A/Act1 signaling has been shown to adversely affect the course of glomerulonephritis by promoting the recruitment of immune cells in particular neutrophils and NET deposition in inflamed kidneys." (PMID 35620115, 2022). "Studies have shown that NETs extracted from the peripheral blood of patients with active systemic lupus erythematosus can express active TF and IL-17A, inducing thrombin production that activates the coagulation mechanism and promotes HSC activation." (PMID 40109341, 2025). "lactis (PTCC 1743) andL. rhamnosus (ATCC 9595) improved disease symptoms in a pristane-induced lupus mouse model and reduced Th17 cell populations and IL-17a levels." (PMID 38828853, 2024). "In contrast, the transfer of lymphocytes from lupus-prone mice, which were pre-treated with IL-23, into Rag1−/−mice, lacking T cells and B cells, induced nephritis, indicating that the IL-23/IL-17A axis contributes to the development of LN." (PMID 35626662, 2022). "In juvenile onset lupus, CREMα has been recognized to drive increased IL-17A expression and reduced IL-2 production in CD4+ T cells." (PMID 35620115, 2022). "The serum levels of IL-6, IFN-γ, IL-10, and IL-17A were higher in HCMVpp65422-439-immunized mice at 12 weeks post-immunization (24 weeks of age, lupus group) compared with NZB/W F1 mice treated with PBS (control group) or adjuvant only (adjuvant group)." (PMID 34824318, 2021). "Of note, IL-17A/A is believed to be of higher pro-inflammatory capacity as compared to IL-17A/F, and in some conditions (namely systemic lupus erythematosus, SLE) the balance is shifted toward IL-17A/A." (PMID 33869291, 2021). "The IL-6 and IL-17A levels were significantly higher in the lupus group compared with the adjuvant and control groups." (PMID 34824318, 2021). "The interleukin-17 (IL-17) family, especially IL-17A, plays an important role in the pathogenesis of systemic lupus erythematosus (SLE)." (PMID 32059488, 2020). "This study demonstrates for the first time that an IL-17A DNA vaccine significantly reduced organ damage and extended survival time in lupus-prone mice." (PMID 32059488, 2020). "Second, anti-IL-17A drugs have been shown to be therapeutically effective in lupus-prone mice, but human studies are needed to determine the exact role of IL-17 in human SLE." (PMID 33597953, 2020). "The proportion of Foxp3+ cells in CD4+IL-17A+ cells was significantly greater in patients with lupus than in those with IgA nephropathy." (PMID 32317002, 2020). "Previous studies showed IFNγ and IL-17A, derived from Th1 and Th17 cell respectively, played a pathology role in lupus progress in MRL/lpr mice." (PMID 33597869, 2020). "Taken together, these data show that immunization with our selected IL-17A epitope DNA vaccine successfully produced anti-IL-17A antibodies, significantly reduced organ damage, and extended survival time in lupus-prone mice." (PMID 32059488, 2020).